MMP9 (matrix metallopeptidase 9)
Diseases named in the same sentence as MMP9 in open-access papers (continued):
Sharing a sentence is not in itself a finding about the gene and the disease.
tumor (continued). "MMP9, which was mentioned earlier as a primary factor promoting angiogenesis, also plays an important role in tumor growth." (PMID 22778768, 2012). "Among the seven MMPs tested, both MMP-3 and MMP-9 were elevated in samples from the tumor site when compared with that from the adjacent normal tissues." (PMID 22873525, 2012). "In response to collagen synthesis, we observed increased expression of matrix metalloproteinases (MMPs), such as MMP-13 and MMP-9, the latter facilitates the tumor cells to invade the extracellular matrix." (PMID 22690114, 2012). "We evaluated the effect of uPAR and MMP-9 knockdown, either alone or in combination with radiation treatment, in pre-established tumor growth." (PMID 22984561, 2012). "Overexpression of tissue MMPs has been correlated with progression in many tumour types, and overexpression of MMP9 has been found in colorectal adenomas and carcinomas." (PMID 22433968, 2012). "We and others have demonstrated that MMPs, among them particularly type IV collagenase MMP-9 (gelatinase B), are especially important in the process of tumor invasion and metastasis, but also in the remodeling and inflammatory processes in IBD." (PMID 23202950, 2012). "MMP-9 protein in tumor tissues was detected by immunohistochemistry and correlated with pre-ALP level." (PMID 22333159, 2012). "In univariate analysis of Dukes’ B tumours, MMP-9 negativity associated with poor survival (p = 0.018), and MMP-9 positivity was an independent prognostic marker in multivariate analysis of these tumours (p = 0.034)." (PMID 23216739, 2012). "We used the Human Tumor Metastasis PCR Array to confirm that two proteases (MMP-9 and cathepsin K) were responsible for coronin 3-related metastasis." (PMID 22974233, 2012). "Matrix metalloproteinase-9 (MMP-9 or gelatinase B, 92 kDa) is the proteases most significantly involved in the degradation of the basement membrane and, thus, in tumor invasion and metastasis." (PMID 23258989, 2012). "Results were evaluated in regard to tumor recurrence and indicated that MMP-9 and TIMP-2 were strongly expressed in tumors that displayed recurrence compared with those that did not." (PMID 22852097, 2012). "IL-8 is known to induce Matrix metalloproteinase 9 (MMP9) which not only plays a role in tumour migration and invasion but also induces angiogenic switch." (PMID 22507529, 2012). "We and others have previously shown that the ablation of host MMP-9 has a minimal impact on tumor/growth or tumor induced osteolysis thus implicating the importance of MMP-2 in the progression of bone metastases." (PMID 22238668, 2012). "The characteristic distribution pattern of MMP-9 showed a diffuse expression in tumour and stromal cells (MMP-9: iOD 791.31 ± 260.52)." (PMID 23107277, 2012). "Expression of GLUT-1, EGFR, MMP-9 and Cathepsin B was found throughout the tumor and the expression patterns closely corresponded to those obtained with FLI." (PMID 22348134, 2012). "Most importantly tumor recurrence was related with higher levels of both MMP-9 (p = 0.003) and IL-8 (p = 0.005)." (PMID 22695075, 2012). "Some level of MMP-9 expression was detected in the cytoplasm of the majority of the samples; 69% (33 of 48) of the cases showed high tumour MMP-9 expression (moderate or strong), while only 4 of 48 cases (8%) tested negative for MMP-9 expression." (PMID 23107277, 2012). "N-acetyl cysteine and selenium have demonstrated inhibition of tumor cell MMP-9 and invasive activities, as well as migration of endothelial cells through ECM." (PMID 22736175, 2012). "Recent in vivo evidence demonstrated that Gr-1+/CD11b+cells are important cellular components that promote tumor development and metastasis by forming tumor endothelium, releasing MMP-9 or suppressing T cell or NK cell function." (PMID 23173040, 2012). "Immunohistochemistry staining showed that MMP-9 proteins were mainly expressed in tumor cytoplasm and positively correlated with elevated pre-ALP levels (r = 0.250, p = 0.015)." (PMID 22333159, 2012).
tumor (continued). "Secondly, LLL12 reduced tumor-associated angiogenic factors (VEGF, MMP-9, angiopoetin, TF and FGF1), probably as a direct consequence of STAT3 inhibition in tumor cells." (PMID 22530037, 2012). "MMP9 mRNA expression dropped to 20% (P = 0.037) in spleen tumor tissue and to 37% (P = 0.022) in liver metastases, compared to control mice." (PMID 22878175, 2012). "Second, the cells expressed higher level of COX Va also had higher expressions and activities of MMP-2 and MMP-9, which had been reported to be related to migration and invasion in different types of tumor cells." (PMID 22748147, 2012). "This study has confirmed that MMP9 levels are raised in those with neoplasia, but a more detailed exploration has also identified that this relationship is non-linear." (PMID 22433968, 2012). "Conversely, the cyclic LRSG peptide [CQVTGALRSGRGKMLLC-NH2, derived from MMP-9 HPX domain residues 615–622] inhibited MMP-9 interaction with the α5β1 integrin, tumor cell invasion, and cell surface gelatinolytic activity." (PMID 23201642, 2012). "VEGF, MMP-2 and MMP-9 are thought to be critically involved in the processes of tumor cell migration, invasion and metastasis." (PMID 22640183, 2012). "Among secreted MMPs, MMP2 and MMP9 (gelatinase A and gelatinase B) are known to play a key role in tumor invasion and metastasis development." (PMID 23226772, 2012). "Another study in androgen-independent prostate cancer described a similar role for CXCL-8 induction of MMP-9 in tumor invasion and tumor-induced neovascularization." (PMID 23342280, 2012). "Among the many MMPs, MMP-2 and MMP-9 are reported to be closely related to the tumor metastasis in ESCC." (PMID 22433565, 2012). "Immnuohistochemistry (IHC) analysis of paraffin-embedded tumor sections with uPAR and MMP-9 specific antibodies was performed in control and pUM-treated (with and without radiation) mice." (PMID 22984561, 2012). "N-acetyl cysteine has been observed to inhibit MMP-9 activity and invasive activities of tumor cells." (PMID 23226724, 2012). "MMP2 and MMP9, the key enzymes for degrading type IV collagen, are believed to play a critical role in tumor invasion and metastasis." (PMID 22479608, 2012). "MMP-9 is a key protease secreted from metastatic cells, which implements proteolytic modification or degradation of the extracellular matrix during tumor cell dissemination." (PMID 22226054, 2012). "The enzymatic activities of MMP-2 and MMP-9 were quantified by gelatin-zymography of the same homogenized tumor tissues and plasma from selected patients." (PMID 21726449, 2011). "The protective role of MMP-9 in tumour growth has also been suggested through angiogenic mechanism by generating anti-angiogenic factors angiostatin and tumstatin." (PMID 22015555, 2011). "Several studies have focussed on the effects of bisphosphonates on macrophage production of MMP-9 and how this has modified tumour progression." (PMID 22005011, 2011). "It has been suggested that CXCL12 promotes tumor invasion by inducing MMP9, which degrades extracellular matrix components." (PMID 22074556, 2011). "These two genes, together with MMP-7, MMP-9, bFGF, IL-1β and IgT7αα are closely related to tumor progression (angiogenesis, invasion and metastasis)." (PMID 21991388, 2011). "We next determined the expression levels of MMP-2 and MMP-9, two key matrix metalloproteases involved in the degradation of the basement membrane, and frequently upregulated in invading tumor cells." (PMID 21595927, 2011). "IL-8 induces MMP-2 and MMP-9 expression in bladder cancer and melanoma cell lines, which contributed to increased tumor cell invasion in vitro." (PMID 22235381, 2011). "Recent work has shown that transgenic mice over-expressing β-arrestin 1 resulted in rapid xenograft tumor progression due to enhanced tumor angiogenesis, mediated by an increase in MMP-9 activity." (PMID 21738726, 2011).
tumor (continued). "The activation of MMP-2 and MMP-9 is in a tumor-specific manner and correlates with metastatic abilities and poor prognosis." (PMID 21955589, 2011). "Snail has been shown to promote tumour cell invasion by either inducing the transcription of MMP-9 or suppression of transcription of E-cadherin." (PMID 21364589, 2011). "In contrast, TNF-α did not modify the expression of a few set of genes known to be regulated by TNFα in tumor cells (such as MMP9)." (PMID 21754991, 2011). "Tumour cells at primary sites induce the expression of MMP-9 in macrophages in the lungs which promotes angiogenesis, aiding tumour cell establishment and growth at this metastatic site." (PMID 22005011, 2011). "Activity of MMP-2 was markedly, activity of MMP-9 was even significantly increased in tumour cells overexpressing FL-L1CAM in vitro." (PMID 21541352, 2011). "Transcript levels of MMP2, MMP9 and IL-17A were measured in another 50 pairs (including tumor and related non-tumor tissues) HCC samples." (PMID 21760911, 2011). "Matrix metalloproteinase 9 (MMP-9) plays an important role in tumor progression, specifically in metastatic capacity, and its constitutive secretion correlates with the degree of tumorigenicity in human keratinocytes." (PMID 22175027, 2011). "In this study, we revealed that AP extracts decreased protein levels of tumor metastasis-related proteins such as MMP-9 and u-PA in KB cells." (PMID 19789215, 2011). "We proposed that TG2 acts at least in part through an activation of NF-κB to upregulate Snail and MMP-9; this then boosts the acquisition of mesenchymal characteristics by the A431 tumor cells." (PMID 21777419, 2011). "Tumour growth is restored following irradiation if the bone marrow in the MMP-9 KO mouse is replaced with wild-type bone marrow." (PMID 21587260, 2011). "In particular MMP-9 is important in the progression of several different tumor types and is thought to be one of the key factors related to increased tumor growth post surgical insult." (PMID 29147264, 2011). "As MMP9 has been reported to be an important factor in tumor metastasis, MMP9 was further characterized in this study." (PMID 21760911, 2011). "The specific importance of the gelatinases MMP-2 and MMP-9 to tumour progression has been delineated in an in vivo study, where combined MMP-2/MMP-9 deficiency in mice significantly impaired tumour angiogenesis and invasion." (PMID 21559216, 2011). "MMP-9 is a matrix metalloproteinase produced by macrophages in response to stimulation by tumour-derived factors." (PMID 22005011, 2011). "FN-1 also increases MMP9 activity, which together with urokinase is involved in tumor cell invasion through the extracellular matrix." (PMID 21062482, 2010). "MMP-2, MMP-9, and uPA are known to be involved in the degradation of extracellular matrix and play a critical role in tumor invasion and metastasis." (PMID 20429953, 2010). "HIF-1α contributed to the induction of SDF-1α in glioblastoma cells, which in turn promoted tumor progression by recruiting MMP9+ vascular modulatory bone marrow cells." (PMID 20490273, 2010). "Studies involving knockout mice of the gelatinase type MMPs (MMP-2 and MMP-9) have shown tumor angiogenesis." (PMID 20671917, 2010). "IL-8 (interleukin-8) has been identified as a chemotactic factor, but recent found that IL-8 and matrix metalloproteinase-9 (MMP-9) are important cytokines which are closely related to the growth and metastasis of tumor." (PMID 20704821, 2010). "Immunohistochemistry for MMP-9 revealed a clear downregulation of this MMP as a result of Dz13 treatment of tumours." (PMID 20334687, 2010). "Daoy-SP2 cells were transfected with MMP-9 cDNA and were injected into the brains of nude mice, and the formation of tumours was monitored." (PMID 20087345, 2010). "In support to this theory, this study revealed high expression of MMP9 in advanced GC tumor tissue, especially nearby the BM." (PMID 20950454, 2010).
tumor (continued). "MMP-2 and MMP-9 are among the known factors that promote tumor cell motility, invasiveness, and epithelial-mesenchymal transition." (PMID 21203518, 2010). "The characteristic distribution pattern of MMP9 was diffused expression in tumor tissue, although small areas of scattered expression were also observed." (PMID 20950454, 2010). "Accordingly, tumor allografts in knockout mice for growth factors such as FGF-2 and MMPs such as MMP-2 and MMP-9 exhibit significantly reduced tumor growth and tumor-induced angiogenesis." (PMID 20804551, 2010). "When IHC was performed, a consistent decrease in MMP-2 and MMP-9 levels was noted in the Dz13 cohort of animals compared to both the saline-treated and Scr-treated tumours." (PMID 20334687, 2010). "Expression of MMP-9 in tumor tissues was markedly decreased in the control group, and incomplete RFA due to low temperature at the target sites significantly increased MMP-9 level in the other groups." (PMID 20667141, 2010). "uPAR and MMP-9, which play critical roles in tumor cell invasion, migration and angiogenesis, have been shown to be associated with lipid rafts." (PMID 21106094, 2010). "The gelatinases MMP-2 and MMP-9, which specifically degrade collagen IV, are important for initiation and development of tumor vascularization." (PMID 23658855, 2010). "The SPARC and MMP-9 are known to interact to regulate many stages of tumour progression including ECM deposition, angiogenesis and metastasis." (PMID 20087345, 2010). "Tumor cells respond to IFNγ by suppressing the expression of MMP-9 and MMP-2 genes, which are involved in the invasion and angiogenesis process of malignant tumors." (PMID 20157617, 2010). "In particular, transgelin is a negative regulator of MMP-9 expression and a suspected tumor suppressor." (PMID 20152043, 2010). "We therefore sought to examine the effects of resveratrol on MMP-2 and MMP-9 expressions in tumor tissues derived from xenografted nude mice by immunohistochemistry and Western blot analysis." (PMID 21209944, 2010). "Our studies indicate MMP-9 induction in Daoy-EV cell-induced angiogenesis, as indicated by an increase in branch points and enhanced tumour growth by 50% compared with that of controls." (PMID 20087345, 2010). "MMP-9 is frequently up regulated by cancer cells and has been shown to affect tumor metastasis and progression." (PMID 20649989, 2010). "MMP9 is secreted from cells and, once activated, is thought to degrade collagen in the extracellular matrix, which promotes the metastasis of tumor cells." (PMID 20534121, 2010). "In this context matrix metalloproteinases and in particular MMP2 and MMP9 are of crucial significance for tumor development and progression." (PMID 20602761, 2010). "Nevertheless, we observed a strong increase of pro-MMP-9 secretion in EDPs-treated tumours and, more importantly, an increase in the expression and activation of the murine counterpart of MMP-1, named murine collagenase-A (Mcol-A)." (PMID 20959825, 2010). "The reduction in VEGF and MMP-9 expressions by macrophages under the influence of ZA has been described to prevent tumour neovascularisation." (PMID 20664588, 2010). "In particular, MMP-9 has been shown to play a critical role in tumor invasion, wound healing, metastasis and angiogenesis." (PMID 21106094, 2010). "We have previously shown that TGF-β derived from the tumor cell compartment in this co-culture model can induce MMP-9 secretion by fibroblasts in a Smad-, ras- and PI3K dependent fashion." (PMID 20352126, 2010). "The promotion of tumor invasion and metastasis has been reported in mice deficient in TNX through the activation of the matrix metalloproteinase 2 (MMP2) and MMP9 genes." (PMID 20969748, 2010). "In oesophageal carcinoma, MMP9 overexpression was significantly correlated with the depth of tumor invasion, lymphatic permeation, nodal metastasis, and pathologic differentiation grade." (PMID 20534121, 2010).
tumor (continued). "The requirement of NF-κB signaling for MMP-9 induction has been confirmed by in vitro and in vivo studies, which demonstrate a relationship between MMP-9 expression and enhancing cell motility and tumor invasion." (PMID 21134288, 2010). "Compared to the low grading group, the expression levels of MMP-2, MMP-9, as well as the tumor edema index (EI), enhanced percentage (EP) and maximum diameters were significantly greater in the high grading group." (PMID 23554622, 2010). "It was therefore possible that EDP-treated tumours contained more monocytes/macrophages than control tumours, which would explain the observed increase of pro-MMP-9 secretion." (PMID 20959825, 2010). "Tumors in stressed animals showed markedly increased vascularization and enhanced expression of VEGF, MMP-2, and MMP-9; it seems that angiogenic processes mediate the effects of stress on tumor growth in vivo." (PMID 20585601, 2010). "Tumor cells excrete elevated levels of NGAL resulting in an increase in local concentration of MMP-9, which can affect various aspects of tumor progression." (PMID 19889214, 2009). "In the in vitro analysis, IFN-γ can reduce the activity of MMP-2 and MMP-9, which are the key modulators of tumor invasion." (PMID 19228418, 2009). "Inactivation of MMP9 by matriptase would be contradictory to the known role of matriptase in tumor invasion." (PMID 19492082, 2009). "In turn, induced tumour cell-derived MIF was critical for invasiveness of tumour cells and MMP9 secretion by macrophages." (PMID 19602265, 2009). "This is consistent with the fact that MMP9 is involved in the degradation of matrix components and thus supports the invasion of tumour cells through basement membrane barriers." (PMID 19568240, 2009). "RECK encodes a membrane-associated MMP regulator protein that is able to suppress tumor invasion and metastasis by negatively regulating MMPs involved in carcinogenesis, namely: MMP-2, MMP-9 and MMP-14 (MT1-MMP)." (PMID 19144199, 2009). "MMP-2 (gelatinase-A) and MMP-9 (gelatinase-B) can both degrade the type IV collagen of basement membranes, the first barrier to tumor invasion." (PMID 19930697, 2009). "In PICP-treated tumors the concurrent low expression of RECK and high expression of MMP-9, and the induction in tumor cells expression of MT1-MMP and MMP-2 will push up the balance of proteolysis compared to control." (PMID 19226458, 2009). "MMP-9 (92 kD gelatinase B) is present in many cells, including endothelial cells, fibroblasts, osteoblasts, cartilage cells, and invasive tumor cells." (PMID 19500428, 2009). "Overexpression of specific MMPs, as the gelatinases A (MMP-2) and B (MMP-9) and stromelysin-3 (MMP-11), have been widely associated to tumour progression and metastasis in different tumours." (PMID 19753302, 2009). "As type IV collagen is one of the integral components of basement membrane (BM), the uncontrolled expression of two type IV collagenases, MMP-2 and MMP-9, is believed to play a critical role in the invasion of BM by tumor cells." (PMID 19930697, 2009). "Together, these findings concur with the observation that the metastatic capability correlates with MMP9 expression in tumour cells (Björklund and Koivunen, 2005)." (PMID 19568240, 2009). "The membrane-anchored MMP-regulator reversion-inducing-cysteine-rich protein with kazal motifs (RECK) regulates tumor invasiveness and, via direct interaction, negatively regulates MMP-9 and inhibits tumor invasion and metastasis." (PMID 19226458, 2009). "Previous studies in flt1-tk deficient mice have shown that MMP-9 is induced by VEGFR1 signaling in lung cells and facilitates metastatic tumor growth in experimental metastasis models (i.e., after intravenous infusion of cancer cells)." (PMID 19763275, 2009). "Among MMPs, matrix metalloproteinase-9 (MMP-9) /gelatinase B has been proved to play an important role in wound healing, angiogenesis, inflammation, tumor invasion and metastasis." (PMID 20514206, 2009).